CCL2 (C-C motif chemokine ligand 2)
Diseases named in the same sentence as CCL2 in open-access papers (continued):
Sharing a sentence is not in itself a finding about the gene and the disease.
infection (continued). "The downregulation of Ccl2 and H3c7 in the glycoprotein group suggests impaired leukocyte migration, which may limit the host’s ability to mount the effective immune response at infection sites." (PMID 40552294, 2025). "The most notable findings were increased levels of CCL2 and CXCL10 pro-inflammatory chemokine protein and mRNA levels in brain homogenates by enzyme-linked immunosorbent assay (ELISA) and reverse transcriptase quantitative PCR (RT-qPCR) assays, respectively, upon infection." (PMID 39745442, 2025). "While the mechanism of SPM recruitment to the site of infection has been previously established as a CCL2 dependent process, the loss of LPMs regardless of the infection route, prompted us to investigate the underlying mechanism behind TRM depletion during acute responses to the parasite." (PMID 38377133, 2024). "Similar to the protein level, the administration of a high dose of GUANKE reduced the transcription of CCL2 (the gene encoding MCP-1), TNFA, and IL6 on the third day after infection, and decreased the transcription of CCL2, TNFA, IL1B, IL6, and IL17C on the fifth day after infection." (PMID 39431894, 2024). "Finally, we asked whether infection altered intestinal expression of monocyte chemoattractant protein-1 (MCP-1), also known as CCL2." (PMID 39140728, 2024). "Endothelial cells from infected young mice displayed elevated expression of chemokines (Cxcl9, Ccl2) and leukocyte adhesion markers (Icam1) underscoring that inflammation of lung endothelium during infection could facilitate leukocyte adhesion and thromboinflammation." (PMID 38911865, 2024). "Notably, CCL2 has also been shown to be secreted by neurons following a TMEV infection." (PMID 38257819, 2024). "Moreover, Ccl2, a chemokine critical for the promotion of monocyte/macrophage migration and infiltration to infection sites, displayed significantly lower expression levels in the lungs of mice infected with cdh1Δ mutant and CDH1OE strains 14 and 21 dpi, in contrast to the H99 group." (PMID 39728387, 2024). "Importantly, dormant C. neoformans retained the ability to provoke gene regulation of monocyte chemotaxis, leading to the secretion of CCL2, chemokine associated with cryptococcal granuloma formation; and CCL4, which was particularly more secreted in this infection." (PMID 38033163, 2023). "Notably, infection by the Delta variant induced significantly higher levels of chemokine mRNAs such as CXCL9, CXCL10, CXCL11, and CCL2 than infection by the wild type and there was negligeable upregulation of cytokine and chemokine mRNA levels in mice infected with Omicron at 3 dpi." (PMID 38257760, 2023). "Hence, tight regulation of CCL2 is crucial to maintain a balanced immune response that permits immunity to infection without causing autoimmune sequelae or a cytokine storm." (PMID 34914635, 2022). "Microglia also express additional subsets of chemokines (Ccl2, Ccl3, Ccl4) with no overlap to those detected in vascular-associated cells, potentially indicating non-redundant mechanisms of T cell recruitment into the brain parenchyma during infection." (PMID 36180478, 2022). "Consequently, the enhanced expression of CCL2/MCP1, PTX3 and TNFα observed after infection with D26 could indicate a heightened disease risk from an NF-kB-driven inflammatory response by an ORF6 deletion variant." (PMID 33399033, 2021). "However, the levels of CCL2 mRNA had decreased by day 5 after infection." (PMID 33477869, 2021). "Inflammatory cells infiltrate the sites of infection at an early stage of the infection with SARS-CoV2 and cause a stormy release of pro-inflammatory cytokines like IL-6, IL-17A, TNFα, IFNγ, IL-1α/β, and chemokines like CC-chemokine ligand 2 (CCL2) as well as CXC-chemokine ligand 10 (CXCL10)." (PMID 33643316, 2021).
infection (continued). "Given that CCL2 is also known to activate microglia and microglial process motility dynamics are altered 48 h after systemic infection, pericytes might modulate microglial process motility and physical dynamics around the vessels in response to infection." (PMID 32317958, 2020). "Furthermore, ssON treatment of RSV-infected mice increased the RSV-induced expression of Cxcl10 and Ccl2, which are both reported to recruit immune cells, such as monocytes, dendritic cells and T cells, to sites of infection or inflammation, thereby aiding in viral clearance." (PMID 33363532, 2020). "However, since PGL-deficient Mm recruits only resident macrophages, the increased iNOS production must be coming from the resident macrophages—i.e., resident macrophages, like TLR-recruited monocytes, also produce more iNOS than Ccl2-elicited permissive monocytes following infection." (PMID 28844797, 2017). "Furthermore, CCL2 expression driven by IFI16 recognition of HSV has been described to facilitate the recruitment of inflammatory monocytes to the infection site, as silencing of p204/IFI-16 resulted in the loss of CCL2 production and significantly more HSV shedding." (PMID 25918478, 2015). "Therefore, the invasion of A. cantonensis may induce some inflammatory factors such as CCL2 secretion in the brain at early infection." (PMID 26070790, 2015). "Finally, we determined whether A3A expression was also induced in infected MDM exposed to anti-CCL2 Ab at the time of infection." (PMID 25608886, 2015). "Hence, the increased expression of IL-6, IL-1β and CCL2 at later stages of infection may act to promote osteoclastogenesis." (PMID 25407789, 2014). "This phenomenon was correlated with reduced CCL2 (MCP-1) expression in db/db liver, which suggests that inadequate macrophage response, due to CCL2 insufficiency, may be to blame for enhanced susceptibility to infection in that environment." (PMID 24618995, 2014). "Furthermore, the antibody array was randomly confirmed by qRT-PCR, and the results showed that pro-inflammatory chemokines including CCL5 and CCL2 and cytokines including IL-6, IL-1β, IL-12, and IL-17 were significantly enhanced after infection with aG and CTN." (PMID 25182681, 2014). "The reason for the higher procoagulant activity with RacL11 is unknown, but similar results have been reported for chemokine gene expression patterns, with RacL11 causing higher levels of CCL2 and CCL3 mRNA in equine PBMC than NY03 or Ab4 after 24 h of infection." (PMID 23497076, 2013). "Interestingly, the chemokine CCL2 has been reported to increase T. cruzi recruitment in vivo, suggesting that pre-existing inflammation may help regulate subsequent tissue infection." (PMID 24312535, 2013). "Moreover, P3 infection significantly enhanced the release of CCL2 and IL-10." (PMID 21269456, 2011). "Hence, the genes Ccl2, Ch25 h, Ifit3, Il1rn, Il6, Parp14, Ptx3, and Socs3 can be defined as a common core of genes expressed early in response to local infection and inflammation caused by Gram-negative stimuli." (PMID 21338499, 2011). "Additionally, whole lungs from anti-Dll1 Ab treated mice at day 7 post-infection had significantly higher protein levels of CCL2 and CXCL1, molecules that play a critical role in the recruitment of monocytes/macrophges and neutrophils into inflammatory lesions." (PMID 22072963, 2011). "The fact that CXCL1 and CCL2 peaked early on the infection when blood RSV RNA was detected at very low levels, and inversely correlated with the peak of RSV RNA loads on day 4 may reflect the different dynamics of viral replication and cytokine production in RSV disease." (PMID 20843364, 2010). "CCL2, IL8 and IP10 expression were upregulated during SARS-CoV, and murine coronavirus infections process, which may recruit monocytes and/or macrophages to sites of infection and be a major cause of lung pathology." (PMID 20614006, 2010).
infection (continued). "In contrast, MDMs are recruited from circulating monocytes in response to inflammation and infection, primarily through the C-C chemokine receptor 2 (CCR2)/monocyte chemoattractant protein-1 (CCL2) axis." (PMID 41514917, 2025). "For instance, infection with JEV in microglial cells has been shown to upregulate the expression of TNF-α, IL-6, and CCL2." (PMID 41221080, 2025). "Early in infection, days 3 and 5, levels of the chemokines CXCL1 and CCL2 were also lower in the brains of co-infected mice." (PMID 39817772, 2025). "The chemokines (CCL2, CXCL1, CXCL8, and CCL20) facilitate the recruitment of monocytes and neutrophils to the site of infection." (PMID 40570043, 2025). "CCL2 expression in infected THP-1 cells was also significantly greater at 0 and 24 hpi, with transcription peaking immediately after infection." (PMID 41280933, 2025). "In vivo, arbutin inhibited the systemic inflammatory response induced by Tg infection, as evidenced by reduced serum levels of IFN-γ, CCL2/MCP-1, and IL-6 four days post-infection." (PMID 41379884, 2025). "Like PMs, THP-1 cells also produced IL-6, CCL4, CCL2, IL-1RA, CCL3, and CXCL9 upon infection with the RSV strain A-0594, although the peak of these responses differed in some cases." (PMID 41280933, 2025). "ROS activate NLRP3 in macrophages, triggering their assembly and the synthesis of compounds like the chemokine (C-C motif) ligand 2 (CCL2, formerly termed monocyte chemoattractant protein-1, MCP-1), which recruits immune cells to the infection site." (PMID 40723899, 2025). "Infection upregulates proinflammatory cytokines such as TNF-α and IFN-γ and chemokines such as CCL2/MCP-1, CCL3/MIP-1α, and CCL5/RANTES, while downregulating the astrocytic glutamate transporter, GLT-1." (PMID 40743275, 2025). "A key function of CCR2 in inflammation involves recruiting monocytes and other components of the immune system to areas of tissue injury or infection, mainly via binding to its ligand CCL2 (monocyte chemotactic protein-1, MCP-1)." (PMID 40909274, 2025). "Host cells upregulate Ccl gene family members (e.g., Ccl2), which bind to receptors (e.g., CCR2) on immune cells, recruiting monocytes, macrophages, and memory T cells to infection sites." (PMID 40539063, 2025). "We used Luminex profiling of serum taken at 6 days post infection in the high dose cohort to analyse the relative levels of 9 cytokines and chemokines: IL-1α, IL-1ß, IL-6, IL-10, IL-12(p70), IL-17, CCL2/MCP-1, GM-CSF and IFN-γ." (PMID 40587585, 2025). "We quantified serum levels of IL-4, IL-6, IL-8/CXCL-8, IL-27, CCL-2, CXCL-9, CXCL-10, and IgG using Luminex and ELISA assays during the acute and subacute phases of infection." (PMID 40711072, 2025). "SGE-enhanced dissemination of virus to joint tissues resulted in higher upregulation of key arthritogenic cytokine transcripts, including TNF-alpha and IL-6, and the chemokines CXCL2, CCL2, and CXCL10 at day 7 post infection." (PMID 41362756, 2025). "Recently, we revealed that infection of MDMs with HIV-1 or HIV-2 differentially regulates production of the β-chemokine, CCL2." (PMID 40507836, 2025). "In contrast, untreated infection networks were dominated by inflammatory mediators (IL6, CXCL10, CCL2, VCAM1, SELE) and antiviral sensors (DDX58, OAS1, IFI44, IFI6), which reflect strong cytokine and interferon-driven immunity." (PMID 41480150, 2025). "Infection also boosted the expression of the CXCL2, CCL2, CCL3, and CCL5 chemokines in female mice, while only CCL2 and CCL3 expression increased in males." (PMID 40143355, 2025). "Macrophages and monocytes produce high levels of chemokines (CCL2, CXCL8, CXCL10, etc.)that can recruit other innate and adaptive immune cells to the site of infection." (PMID 40472051, 2025). "Our work demonstrates that human retinal organoids have the capacity to respond to T. gondii tachyzoites, with developing and matured organoids up-regulating CCL2 and CXCL10 transcripts at multiple time points following infection." (PMID 40137771, 2025).
infection (continued). "We noted that infection in female TLR7ko mice boosted IFNG, CCL2, CCL3, and CCL5 expression, although significantly less compared to the female WT group, but these responses were completely blunted in TLR7ko male mice." (PMID 40143355, 2025). "Macrophages also produce chemokines such as CCL2 (MCP-1) to attract monocytes and other immune cells to the site of infection." (PMID 40136728, 2025). "On the other hand, infection with SFV/TNFα specifically upregulated the amount of IL-6, CCL2, CCL3, CCL7 and CCL20 (p < 0.0001)." (PMID 40547518, 2025). "The heightened infection risk in GD may be attributable to dysfunction of immune cells, including monocytes, macrophages, dendritic cells, T cells, and B cells, as well involvement of cytokines, such as MCP1/CCL2, CXCL8/IL8, CXCL1, IL-1β, IFNγ, and TNFα, are implicated in GD progression." (PMID 40980139, 2025). "Our findings demonstrate that primary monocytes and related THP-1 cells are permissive to abortive infection by RSV, leading to increased expression of proinflammatory cytokines and chemokines, including IP-10, IL-6, and CCL2." (PMID 41280933, 2025). "Similar to CCL2, CCL3 plays a vital role in the recruitment and activation of monocytes and macrophages, including T cells to sites of infection and It involved in immune response and the regulation of antiviral defense." (PMID 40552037, 2025). "Several cytokines (TNF, IL-1β) and chemokines (CXCL10, CCL2, CCL5) were reduced in the brains of Rag1–/– animals at day 14 after infection, which were restored or exceeded WT levels mainly with Th1 adoptive transfer, whereas Th17 cells were less effective." (PMID 39989461, 2025). "In the case of MHV-JHM infection, changes in expression (from 0% to 100%) were visible in IL-6, IL-18, IL-33, ENA-78 (CXCL5), GRO alpha (CXCL1), IP-10 (CXCL10), MCP-1 (CCL2), MIP-1 beta (CCL4), MIP-2 alpha (CXCL2), RANTES (CCL5), and TNF alpha." (PMID 40358160, 2025). "We found that infection of PBMC by the neurovirulent HIV-1ADA and treatment of PBMC by recombinant Tat of HIV-1YU-2 strain, both up-regulated chemokines CCL-2, CCL-3, and CCL-4 to significant levels." (PMID 40313367, 2025). "One day after infection, the hemogram is still normal, but circulating TNF-α, IL-1β, and CCL2 were markedly lower in infected hypothyroid mice with respect to euthyroid mice, while CXCL10 levels were higher." (PMID 41263555, 2025). "Quantitative PCR analysis revealed increased mRNA levels of proinflammatory cytokines and chemokines (Tnf, Il6, Il1b, Ccl2, Cxcl1, and Cccl2) in SARS-CoV-2-infected lungs compared with those in naïve lungs on days 2 and 5 post-infection." (PMID 40162785, 2025). "infection alters the secretome of decidual stromal cells, leading to an overproduction of CXCL8 and CCL2, which in turn impairs trophoblast invasive capacity." (PMID 40943115, 2025). "Top downregulated DEGs in bystander cells indicated a decreased enrichment of certain pro-inflammatory cytokines and signaling molecules in ADE compared to conventional infection conditions, including CXCL11, CXCL10, CCL2, DOCK4, STAT1, and JAK2." (PMID 39902963, 2025). "Real-time PCR analysis of mRNA from whole brain tissue revealed elevated expression of proinflammatory mediators ll-6, Il-1β, Ccl2, Cxcl9, and Cxcl10 in both the WT and eNOS+/− mice 3 days post-MA10 infection." (PMID 40573374, 2025). "In conclusion, our current and previous studies reveal that infection of MDMs with HIV-2 induced the production of similar levels of M-CSF but lower levels of CXCL7 and CCL2 compared to MDMs infected with HIV-1." (PMID 40507836, 2025). "Elevated chemokines like C-C Motif Chemokine Ligand 2 (CCL2) and C-C Motif Chemokine Ligand 3 (CCL3) suggested increased recruitment of more immune cells to the infection site." (PMID 39928675, 2025).
infection (continued). "The expression of IL-1β, IFN-α2, IFN-γ, TNF-α, MCP-1 (CCL2), IL-6, IL-8 (CXCL8), IL-10, IL-12p70, IL-17A, IL-18, IL-23, and IL-33 was assessed in apical washes at different time points after infection using a 13-plex immunoassay." (PMID 40143308, 2025). "Chemokines (CCL2, CCL3L1, CCL4, CXCL9, CXCL10, CXCL11, and XCL1) were also significantly upregulated after infection." (PMID 38698849, 2024). "T cells secrete numerous chemokines including CCL2, CCL3, and CCL4, which direct cellular recruitment to the site of infection." (PMID 38977711, 2024). "CCL2 and CXCL10 transcripts were upregulated after 30 days and 60 days of infection, as were IFN-a, IFN-b, ISG15, and IFI16 transcripts." (PMID 38737767, 2024). "Infection with NCTC10562 was seen to induce a variety of inflammatory cytokines and chemokines including IP-10, RANTES/CCL5 and MCP-1/CCL2." (PMID 39286811, 2024). "We also analyzed the expression of chemokines CCL2, CCL3, and CCL4, which are synthesized in response to infection and play an important role in the recruitment of monocytes/macrophages to inflammation sites." (PMID 38674602, 2024). "The inflammatory cytokines TNFα, IL-4, IL-6, IL-13, IL-10, IL-12 (P40), and IL-12 (P70) along with chemokines including CCL2, CCL3, and CCL5, were significantly elevated in the plasma of c-Flip+/–mice on day 2 post-infection compared that of WT mice." (PMID 39038037, 2024). "Monocyte chemoattractant protein 1 (MCP-1), also known as CCL2, is a chemoattractant chemokine that recruits monocytes and dendritic cells to the site of infection." (PMID 38251391, 2024). "Overall, these data show reduction of MMP-9 and CCL2 concentrations, and an induction of IFN-β and CXCL10 across time, as a result of infection." (PMID 40295794, 2024). "In our study, we found that TLR7 was involved in the immunopathogenesis of infection with RABV, and the expression of CCL2, CXCL10 and IL-6 were significantly increased in the terminal stage of infection with RABV." (PMID 39273091, 2024). "Our results show that CC chemokine receptors and their ligands, which are necessary for neutrophil mobilization and recruitment to the lungs during infection, are down regulated in human CHIP carriers (e.g., CXCL1, CXCL5) and mice (e.g., CCR2, lung CCL2)." (PMID 38573824, 2024). "Similar to ROSS strain infection, the expression of TNF-α, IL-6, CCL-2, and IL-10 was reduced upon etravirine treatment compared with DMSO treatment under the LR2006 OPY1 strain challenge." (PMID 39339151, 2024). "By 16 hours after infection, chemokine expression was increased in both WT CHIKV–infected WT and MARCO–/– mice in comparison with mock-infected mice; however, Ccl2, Cxcl1, and Cxcl9 expression remained significantly higher in the dLN of WT mice." (PMID 38194268, 2024). "Our data show that JCPyV-infected choroid plexus epithelial cells at 7 days post-infection, which represents two full viral life cycles, secrete a signature of proinflammatory chemokines, including CXCL8, CXCL5, CXCL6, and CCL2." (PMID 38874395, 2024). "In comparison to uninfected mice, the levels of IL-1β, IL-6, IL-12p70, TNF-α, CCL2, CXCL2, GM-CSF, and G-CSF were significantly increased in both PLF and serum after infection." (PMID 38951957, 2024). "The monocyte chemoattractants CCL2 and CCL4 were significantly increased in mice infected with both Em and Bb, relative to vehicle or single Bb infection, and CCL7 was significantly increased in co-infected mice relative to Em alone." (PMID 39229265, 2024). "While we did not detect vaccination-associated differences in plasma levels for IL-5, IL-23, IL-33, and CCL2/MCP-1, we observed a step-wise reduction of IL-18 levels after post-infection vaccinations in individuals with ongoing PCC." (PMID 38316833, 2024). "We observed that concentrations of the monocyte chemoattractants CCL2, CCL3, CCL4, CCL5, and CCL7 were significantly increased in mice inoculated with both pathogens, relative to vehicle and single Bb infection." (PMID 39229265, 2024).